ALB (albumin)
Diseases named in the same sentence as ALB in open-access papers (continued):
Sharing a sentence is not in itself a finding about the gene and the disease.
Hypertension (continued). "Even after adjusting some variables in logistic regression models, such as age, hemoglobin, albumin, estimated glomerular filtration rate, ASA, influid amount, blood loss, hypertension, and coronary artery disease, quintiles 3, 4, and 5 remained independently associated with post-operative AKI." (PMID 35899215, 2022). "Additionally, in this study, the median serum albumin value significantly decreased as the severity of pregnancy-related hypertensive disorders increased." (PMID 36140589, 2022). "BMI, albumin, hypertension, TLNs, and ratio of PLNs were independent predictors of DDASD." (PMID 33510284, 2021). "We performed restricted cubic spline regression analysis to evaluate the linearity of the relationship between serum albumin concentration and the risk of hypertension development and found that there was a non-linear relationship between them." (PMID 34050200, 2021). "The most common treatment-related AEs included alanine aminotransferase or aspartate aminotransferase elevation, total bilirubin elevation, decreased platelet, hypertension, fever, fatigue, decreased albumin, leukocytopenia, pain, nausea, and diarrhea, which were mostly grade 1/2." (PMID 34670506, 2021). "While the diagnosis of hypertension and its various forms (white coat, masked, true hypertension) and proteinuria (urine albumin/creatinine) is well-established and used by most physicians, the assessment of subclinical CV injury is still not routinely done in all children with diabetes type 1." (PMID 34988037, 2021). "Second, either the determination of serum albumin concentration or the development of hypertension might be influenced by a wide variety of factors promoting vascular endothelial dysfunction." (PMID 34050200, 2021). "Patients experiencing the primary endpoint were older; had lower BMI and GNRI values; had a lower prevalence of hypertension and dyslipidemia; had lower statin use; and had lower hemoglobin, albumin, HDL-cholesterol, and LDL-cholesterol levels than those who did not experience the primary endpoint." (PMID 33530352, 2021). "Univariate and multivariate Cox analyses revealed that the body mass index, serum albumin level, hypertension, number of total dissected axillary lymph nodes, and ratio of positive axillary lymph nodes were independent predictors of postoperative drainage duration in the training cohort." (PMID 33510284, 2021). "In the univariate analysis, the male sex, underlying malignancy, DM, hypertension, elevated serum ALT levels, decreased serum albumin levels, increased hs-CRP and PCT levels, maximal diameter of abscess, PCD insertion, and culture positivity were associated with prolonged hospitalization." (PMID 33573593, 2021). "In the LR group, body mass index and preoperative hemoglobin and albumin levels were favorable risk factors of OS and CSS, whereas hypertension and pathologic T3-4 and N1 stages were unfavorable risk factors of both OS and CSS; a Fuhrman nuclear grade 3-4 was a risk factor of CSS only (p < 0.05)." (PMID 34262859, 2021). "In addition, serum albumin and creatinine levels are considered indicators of renal dysfunction in hypertension, and it is known that albumin decreases, and creatinine increases in renal function abnormalities by hypertension." (PMID 34956385, 2021). "All statistically significant measurements between the PD and non-PD groups based on the univariate analysis, including age, operative time, duration of anesthesia, cases with hypertension, serum albumin and PNI were subjected to multivariate logistic regression analysis." (PMID 34511076, 2021). "However, serum albumin levels are elevated in patients with high blood pressure, even though albumin is negatively associated with cardiovascular disease." (PMID 33639645, 2021). "Even in the absence of proteinuria or edema in pregnant women with hypertension, decreased serum albumin concentration should be a cause of concern." (PMID 32245416, 2020).
Hypertension (continued). "Most GPs (n = 288, 95.4%) routinely ordered creatinine, urea, and electrolytes for hypertension; however, only half or less of the GPs routinely ordered lipid profile (n = 156, 52.0%), HbA1c (n = 121, 39.9%), or urine albumin to creatinine ratio (n = 102, 33.7%)." (PMID 33278890, 2020). "Additionally, ALB levels in pregnant COVID-19 patients with hypertension were significantly lower than that in pregnant COVID-19 patients without hypertension (33.67 vs. 36.08, p < 0.05)." (PMID 33117727, 2020). "The value of NRI and IDI for detecting CTRCD reached statistical significance when baseline RDW value was added to the model including cumulative dose of anthracycline, EF, albumin and hypertension; 0.9252 (95%CI 0.4103–1.4402, P < 0.001) for NRI and 0.1125 (95%CI 0.0078–0.2171, P = 0.035) for IDI." (PMID 33330656, 2020). "We explored whether the effect of chloride was modified by vascular endothelial dysfunction defined by albuminuria and observed a stronger effect of uCl on development of hypertension with higher urinary albumin excretion in concurrence with previous work." (PMID 32023312, 2020). "The predictors of AKI at ICU admission included hypertension [odds ratio (OR) = 1.44, p 0.017], high serum creatinine concentration [OR = 3.54; p < 0.001], low serum albumin concentration [OR = 1.42, p 0.015], high APACHE II score [OR = 2.10; p < 0.001] and high SAPS 3 [OR = 1.75; p < 0.001]." (PMID 31792326, 2019). "The low, medium, and high groups differed in terms of sex, history of hypertension, presence of edema and hematuria, levels of fibrinogen, IgG, C4, total protein (TP), ALB, and serum creatinine (SCr), and estimated glomerular filtration rate (eGFR) evaluated by the MDRD equation." (PMID 31057017, 2019). "Based on previous studies, urinary albumin (ALB) had the potential to be a marker for hypertension." (PMID 30809144, 2019). "Chronic cardiopulmonary disease, hypertension, and glucose and lipid metabolism disorders, which occur at a higher incidence in the elderly population, could affect the BMI values or albumin level in elderly patients." (PMID 30135506, 2018). "In a cohort of individuals with non-hypertension or non-diabetics showed low grade urinary albumin excretion was associated with increased risk of CVD and mortality, though the increase was modest in terms of the absolute event rates." (PMID 30167324, 2018). "Additionally, male sex; older age; concomitant disease, including hypertension; and symptoms, including fever, thrombocytopenia, lymphopenia, and low albumin concentration, were related to MERS severity or secondary disease." (PMID 29716568, 2018). "Multivariable linear regression analysis further verified a significant relationship between IL-34 level and NT-proBNP level (β = 0.171, P < 0.001) after adjusting for age, sex, BMI, history of hypertension, history of DM, and levels of hsCRP, hemoglobin, albumin, HbA1c, as well as eGFR." (PMID 30050466, 2018). "Age, hospitalization, antithrombotic drug use, comorbidities (hypertension, ischemic heart disease, and cerebrovascular disease), and laboratory findings (serum albumin, serum creatinine, white blood cell count, and hemoglobin levels) were significantly different between cases and controls." (PMID 30158969, 2018). "Conversely, hypertension (OR 2.400, 95%CI 1.180–4.883, p = 0.016), preoperative albumin level (OR 0.488, 95%CI 0.242–0.987, p = 0.046), and synthetic colloids infusion (OR 4.871, 95%CI 1.122–21.148, p = 0.035) were significantly associated with AKI after surgery." (PMID 30142190, 2018). "Hypercholesterolaemia, random blood glucose, and spot urine albumin: creatinine ratios showed no signs of associated risk with hypertension." (PMID 30057806, 2018).
Hypertension (continued). "Patients with poor clopidogrel response were more likely to be female (cases versus controls: 32.1% versus 15.15%, P = 0.007) and have hypertension (cases versus controls: 75.31% versus 58.59%, P = 0.018) and lower albumin levels (cases versus controls:38.11 ± 4.38 versus 39.83 ± 5.64, P = 0.026)." (PMID 28358842, 2017). "PDE5i treatment prevented the development of DN-related hypertension (P < 0.001), the increase of urine albumin creatinine ratio (P < 0.01), the fall in glomerular filtration rate (P < 0.001), and improved renal resistive index (P < 0.001) and kidney microcirculation." (PMID 28294194, 2017). "The adsorbents HA and hypertension were more efficient in the separation of albumin process." (PMID 27376149, 2016). "Patients who developed recurrent CVD exhibited more hypertension (P = 0.004), diabetic nephropathy (P = 0.012), higher mean systolic BP (P = 0.006), urinary albumin excretion (P = 0.015), and mean triglyceride level (P = 0.035) compared to patients who did not have recurrent CVD." (PMID 27741306, 2016). "Increased albumin TER in obesity associated with increased fat mass, hypertension and inflammation suggest glycated albumin is not a reliable measure of glycemic control and formation of AGEs in obesity." (PMID 27338619, 2016). "Patients who developed recurrent CVD also exhibited hypertension (P = 0.004), diabetic nephropathy (P = 0.012), higher mean systolic blood pressure (P = 0.006), urinary albumin excretion (P = 0.015), and mean triglyceride level (P = 0.035) than did patients without recurrent CVD." (PMID 27741306, 2016). "After adjusting for potential confounders (demographics, BMI, DM2, alcohol consumption, smoking status, total cholesterol, albumin, weight change, hypertension, heart disease, stroke, and claudication), a significant association remained (OR = 1.24, 95 % CI:1.07–1.45, p = 0,04)." (PMID 26949420, 2016). "Our findings indicate an association between serum albumin levels and the deterioration of circadian BP rhythm among essential hypertensive patients along with the identification of a non-dipper pattern in more than two-thirds of patients." (PMID 27276394, 2016). "In conclusion, our findings indicate an association between serum albumin levels and the deterioration of circadian BP rhythm among essential hypertensive patients, with a non-dipper pattern identified in more than two-thirds of the patients." (PMID 27276394, 2016). "Conversely, we speculate that low salt diet may mitigate the intrarenal RAS activation in pathological states, including hypertension, and therefore preserve renal handling of albumin." (PMID 26495970, 2015). "We investigated whether urinary albumin could predict the development of hypertension and future increases in blood pressure in the normotensive general population." (PMID 25674745, 2015). "However, there are several possibilities supporting that urinary excretion of albumin predicts a new onset of hypertension." (PMID 25674745, 2015). "In addition to peripheral arterial occlusive disease, cancer, and serum albumin, we observed the presence of a history of hypertension showed a protective effect on early death, and a history of stroke exerted a negative impact on overall survival." (PMID 25856435, 2015). "The concept that urinary albumin predicts future development of hypertension was further reinforced by the finding that not only UACR at baseline, but also a yearly increase in UACR was independently correlated with the longitudinal increase in systolic blood pressure." (PMID 25674745, 2015). "This observational study does not provide a causal relationship between urinary albumin and the development of hypertension." (PMID 25674745, 2015).
Hypertension (continued). "In subgroup analysis, significant relationship of serum GGT level with both low-grade albuminuria and increased urinary albumin excretion were detected in women, younger subjects, overweight subjects and in those with hypertension or glomerular filtration rate greater than 90 (all P <0.05)." (PMID 25500578, 2014). "The patient was treated for hypertension and she received albumin replacement." (PMID 25883727, 2014). "ΔHS correlated positively with age, heart disease, diuretics use, anti-hypertension drug use, baPWV, and urine protein, but negatively with the male gender, body mass index, eGFR, serum albumin, cholesterol, and hemoglobin levels in univariate linear regression analysis." (PMID 25386836, 2014). "Significant relationship of serum GGT level with both low-grade albuminuria and increased urinary albumin excretion were detected in women, younger subjects (age less than 60 years), overweight subjects and in those with hypertension or GFR greater than 90 (all P<0.05)." (PMID 25500578, 2014). "Data from essential hypertension showed arterial stiffness correlated with albumin excretion rate." (PMID 24245955, 2013). "Moreover, some studies suggest an independent prognostic value of high blood pressure at presentation ?r during follow-up, hematuria, family history of hypertension or chronic renal failure, serum albumin level, age, and male gender." (PMID 22719981, 2012). "Using multivariate logistic regression, we identified eight independent risk factors: fibrinogen (FIB), albumin (ALB), atherogenic index of plasma (AIP), low-density lipoprotein cholesterol (LDL-C), body mass index (BMI), classification of DR, gender, and history of hypertension." (PMID 40391008, 2025). "This study shows that, in patients with uncontrolled stage I/II hypertension, RDN is associated with more favorable changes in capillary density at 12‐month follow‐up, compared with control patients, as well as with a non‐significant trend toward improvement of albumin excretion levels." (PMID 40544439, 2025). "Consistent with most research, our current work revealed that elevated SII was correlated with increased levels of FPG, TC, triglycerides, LDL-C, and homocysteine, a decreased level of serum albumin, and a high prevalence of hypertension, which may have contributed to the development of ISR." (PMID 38409069, 2024). "However, no noteworthy disparities emerged between the two groups concerning gender distribution, primary disease etiology, concurrent hypertension, BMI, PA, ALB, ALP, BUN, CysC, SUA, TC, HDL-C, LDL-C, P, iPTH, dialysis vintage, dialysis shift, vascular access type, or Kt/V adequacy (p > 0.05)." (PMID 39839624, 2024). "Notably, eGFR, DM, cancer, cardiovascular disease, and CRP log were baseline factors that were positively correlated with the MIS, whereas age, hypertension, hemoglobin level, albumin level, cholesterol log, phosphorus level, BMI, and muscle mass index were negatively correlated with the MIS." (PMID 39683409, 2024). "Therefore, it is reasonable to suggest that GERD, peptic ulcer disease, ileus, underweight, DM, albumin, hemoglobin, and hypertension may be involved in common pathways contributing to all-cause mortality in patients with chronic schizophrenia." (PMID 38831863, 2023). "While elevated urinary albumin excretion was more likely to precede hypertension, conclusions regarding causality effects could not be provided." (PMID 37392357, 2023). "Living donor candidates who did not meet the blood pressure criteria could be a living donor if they met the marginal criteria, which included candidates with hypertension who had maintained their blood pressure at ≦130/80 mmHg and had an albumin/Cr ratio of <30 mg/g Cr." (PMID 36275464, 2022).
Hypertension (continued). "In this regard, guidelines for the management of hypertension recommend routine assessment of hypertension-induced renal damage by using simple renal function parameters (serum creatinine and eGFR) together with the investigation of albuminuria (dipstick or urinary albumin creatinine ratio)." (PMID 35743755, 2022). "Also, low albumin to globulin ratio (AGR) has been associated with vascular adverse events and red blood cell aggregability in both acute and chronic CVD, including its risk factors such as old age, diabetes, hypertension, and renal insufficiency." (PMID 35881574, 2022). "However, a retrospective study of normotensive Japanese (N = 2240) reported a negative association between blood albumin and risk of hypertension." (PMID 34784307, 2022). "Maternal albumin levels before delivery (beta coefficient −0.83, p = 0.043) and increased placental syncytial knots (beta coefficient 0.71, p = 0.026) are important parameters that are closely related to disease severity in women with pregnancy-related hypertensive disorders." (PMID 36140589, 2022). "Furthermore, the top 10 risk factors for determining DFU severity when measured by mean decrease accuracy were serum albumin level, neutrophil percentage and hemoglobin level in whole blood, plasma fibrinogen level, HbA1c, eGFR, hypertension, SUA level, DR, and sex." (PMID 34465375, 2021). "Serum albumin had a non-linear relationship with the risk of hypertension development." (PMID 34050200, 2021). "Moreover, lysozymes from egg albumin have antibacterial, antiviral activities (viral bronchitis, herpetic lesions, stomatitis, etc.), while ova albumin extracted from eggs is effective in preventing hypertension." (PMID 34504421, 2021). "In addition to clinical predictors, such as age, sex, and a history of cardiovascular disease and hypertension (negative risk), we determined that NT-proBNP, cholinesterase, and albumin were among the most significant prognostic markers in the entire cohort." (PMID 32732919, 2020). "This may indicate that the increased filtration of albumin in the glomerulus, potentially as a result of endothelial damage, and not albuminuria per se may link albuminuria to hypertension and increased CVD risk." (PMID 31511532, 2019). "Multivariable analysis showed the incidence of positive urine dipstick albumin was higher among the elderly and those with elevated serum creatinine, high hemoglobin A1c, or high blood pressure; however, low-dose aspirin did not increase the risk of positive urine dipstick albumin." (PMID 26808136, 2016). "Thus, even a mild increase in urinary albumin could potentially be an early symptom of developing hypertension." (PMID 25674745, 2015). "Some patients with easily controlled hypertension who meet other defined criteria (e.g., >50 years of age, GFR ≥ 80 mL/min, and urinary albumin excretion < 30 mg/day) may represent a low-risk group for development of kidney disease after donation and may be acceptable as kidney donors." (PMID 22655169, 2012). "These fragments may be a result of the proteolysis of serum albumin, although currently no information is available on the association of serum albumin with hypertension in rats." (PMID 22416803, 2012). "Optimal control of hyperglycaemia, including maximal suppression of urinary albumin excretion by angiotensin-converting enzyme inhibitors (ACEIs) or angiotensin II receptor blockers (ARBs) in diabetic patients with persistent microalbuminuria, and hypertension can limit progression of CKD to ESRD." (PMID 21777480, 2011). "The ISR (+) group showed a higher prevalence of hypertension and active smoking, as well as higher CRP, glucose, and neutrophil levels, but lower albumin and lymphocytes (all p < 0.05)." (PMID 41827923, 2026). "Higher values of features such as HbA1c, Crea, AST, Lp(a), Apo Ai, hypertension, smoking status, age, fibrinogen (FIB), HDL-C, albumin (ALB), glucose (Glu) and total protein (TP)." (PMID 40475993, 2025).